ADRA2B (adrenoceptor alpha 2B)
Description:
Alpha-2 adrenergic receptors are G protein-coupled receptors for catecholamines that activate G(i/o) protein pathway, thereby promoting adenylyl cyclase inhibition, ERK1/2 stimulation, and voltage-gated calcium channels suppression. Control a variety of physiological processes, such as regulation of blood pressure, lipolysis and insulin release. The rank order of potency for agonists of ADRA2B is clonidine > norepinephrine > epinephrine = oxymetazoline > dopamine > p-tyramine = phenylephrine > serotonin > p-synephrine / p-octopamine. For antagonists, the rank order is yohimbine > chlorpromazine > phentolamine > mianserine > spiperone > prazosin > alprenolol > propanolol > pindolol.
Synonyms: Alpha-2BAR; ADRA2L1; ADRA2RL1; ADRARL1; ALPHA2BAR; FAME2
Tractability: Small molecule: an approved drug acts on it; a structure with a bound ligand is known; a high-quality ligand is known; it belongs to a druggable protein family. Antibody: UniProt places it where antibodies can reach, with high confidence; its Gene Ontology location is reachable by antibodies, with high confidence; UniProt predicts a signal peptide or a membrane-spanning region. PROTAC: a small molecule that binds it is known. Other modalities: an approved drug acts on it.
Target class: Small molecule receptor (family A GPCR); Adrenergic receptor; Monoamine receptor; Membrane receptor; Family A G protein-coupled receptor
Chemical probes: ASCORBIC ACID (high quality), BAY-6096 (high quality)
Safety:
Unwanted effects reported when the protein is acted on. In parentheses: how it was acted on, where the effect was seen, and who reports it.
cardiac ischemia (activation, acute dosing; nervous system, cardiovascular; source: Lynch et al. (2017))
decreased blood pressure (inhibition, acute dosing; nervous system, cardiovascular; source: Lynch et al. (2017))
decreased pain (activation, acute dosing; nervous system, cardiovascular; source: Lynch et al. (2017))
decreased survival (inhibition, developmental toxicity; nervous system, cardiovascular; source: Lynch et al. (2017))
increased blood pressure (activation, acute dosing; nervous system, cardiovascular; source: Lynch et al. (2017))
increased heart failure (activation, acute dosing; nervous system, cardiovascular; source: Lynch et al. (2017))
increased heart rate (activation, acute dosing; nervous system, cardiovascular; source: Lynch et al. (2017))
sedation (activation, acute dosing; nervous system, cardiovascular; source: Lynch et al. (2017))
skeletal muscle tremor (activation, acute dosing; nervous system, cardiovascular; source: Lynch et al. (2017))
Gene: Protein-coding gene on chromosome 2 (96,112,876 to 96,116,571, reverse strand). Ensembl gene ENSG00000274286.
Subcellular location: Cell membrane
Subcellular location (Human Protein Atlas): Vesicles; Cytosol
Pathways (Reactome):
Signal Transduction: Adrenoceptors; G alpha (i) signalling events; G alpha (z) signalling events
Hemostasis: Adrenaline signalling through Alpha-2 adrenergic receptor
Gene Ontology:
Molecular function: alpha2-adrenergic receptor activity; epinephrine binding; protein binding; adrenergic receptor activity; G protein-coupled receptor activity
Biological process: adenylate cyclase-inhibiting adrenergic receptor signaling pathway; adenylate cyclase-inhibiting G protein-coupled receptor signaling pathway; adrenergic receptor signaling pathway; epidermal growth factor receptor signaling pathway; G protein-coupled receptor signaling pathway; positive regulation of MAPK cascade; positive regulation of neuron differentiation; positive regulation of phosphatidylinositol 3-kinase/protein kinase B signal transduction; cell-cell signaling; negative regulation of epinephrine secretion; negative regulation of norepinephrine secretion; female pregnancy; platelet activation; positive regulation of blood pressure; positive regulation of uterine smooth muscle contraction; regulation of smooth muscle contraction; regulation of vascular associated smooth muscle contraction; regulation of vasoconstriction
Cellular component: cell surface; plasma membrane; membrane
Genetic constraint (gnomAD): Loss-of-function variants: 17 observed, 16.33 expected, observed/expected ratio (o/e) 1.04, 90% interval 0.71 to 1.56. The upper end of that interval is the gene's LOEUF score, 1.56, which puts it in group 6 of 6, group 1 being the genes least tolerant of losing a copy. Missense variants: 603 observed, 624.16 expected, observed/expected ratio (o/e) 0.97, 90% interval 0.9 to 1.03. Synonymous variants: 249 observed, 276.21 expected, observed/expected ratio (o/e) 0.9, 90% interval 0.81 to 1.
Gene-disease validity (ClinGen):
ClinGen rates the evidence that ADRA2B causes each of these diseases.
epilepsy (autosomal dominant): Refuted. A brain disorder characterized by episodes of abnormally increased neuronal discharge resulting in transient episodes of sensory or motor neurological dysfunction, or psychic dysfunction.
Homologues: Orthologues: chimpanzee ADRA2B (98% identical), macaque ADRA2B (96% identical), pig ADRA2B (90% identical), dog ADRA2B (88% identical), guinea pig ADRA2B (88% identical), rat Adra2b (84% identical), mouse Adra2b (83% identical), rabbit ADRA2B (82% identical), tropical clawed frog adra2b (56% identical), zebrafish adra2b (52% identical), Caenorhabditis elegans ser-5 (22% identical). Paralogues in human: ADRA2A (50% identical), ADRA2C (50% identical), DRD2 (29% identical), ADRA1B (28% identical), ADRA1D (27% identical), ADRA1A (26% identical), ADRB1 (24% identical), ADRB3 (24% identical), ADRB2 (22% identical), GPR101 (18% identical), OR5T1 (14% identical), OR5T2 (14% identical), and 6 more.
Diseases named in the same sentence as ADRA2B in open-access papers:
ADRA2B is named in the same sentence as 29 diseases in open-access papers, as found by Europe PMC text mining. Sharing a sentence is not in itself a finding about the gene and the disease. The quoted sentences say what the papers report.
Hypertension (3 papers, 2018 to 2024). The presence of chronic increased pressure in the systemic arterial system. "Deletion polymorphisms or different variants of ADRA2B and ADRA2C are known to be related to endothelial dysfunction, heart failure, and hypertension." (PMID 33240096, 2020). "In conclusion, there is substantial evidence that genetic variability in ADRA2A and ADRA2B genes influences α2-adrenoceptor function, leading to hypertension due to modulating vascular resistance, endothelial function, and sodium homeostasis in different cohorts." (PMID 33240096, 2020).
alcohol abuse (1 paper, 2018). The use of alcoholic beverages to excess, either on individual occasions ("binge drinking") or as a regular practice. "The association between gene ADRA2B and “alcohol abuse” ICD-9 305.00 (mental disorders category) is observed as most significant result for functional annotation filter 2 (P-value = 3.88e − 10)." (PMID 29545597, 2018).
cerebrovascular disorder (1 paper, 2021). A disorder resulting from inadequate blood flow in the vessels that supply the brain. "Polymorphisms of the ADRA2B gene have been linked to cerebrovascular disorders." (PMID 33788842, 2021).
heart failure (1 paper, 2023). Inability of the heart to pump blood at an adequate rate to meet tissue metabolic requirements. "These include both serious ADRs (heart failure for ADRA2B, DRD1, and DRD2 activation) and lower severity effects (sleep or memory impairments for several targets)." (PMID 37468498, 2023).
hepatocellular carcinoma (1 paper, 2019). A malignant tumor that arises from hepatocytes. "The overall association scores for hepatocellular carcinoma were 0.210 for HOXD9, 0.174 for NDST3, 0.111 for PZP, 0.106 for E2F8, 0.061 for ADRA2B, and 0.029 for COL15A1." (PMID 31754347, 2019).
ischemic heart disease (1 paper, 2020). "Our results identify ADRA2B as a novel therapeutic target in ischemic heart disease." (PMID 32958803, 2020).
motor neuron degeneration (1 paper, 2022). "Our findings were in line with the study reporting that treatment with ADRA2B agonist (rilmenidine) worsened motor neuron degeneration in SOD1G93A mice." (PMID 35837482, 2022).
schizophrenia (1 paper, 2023). A major psychotic disorder characterized by abnormalities in the perception or expression of reality. "In addition, polymorphisms in adrenoceptor alpha 2B (ADRA2B) are associated with suicidality among patients diagnosed with schizophrenia." (PMID 38069051, 2023).
inflammation (1 paper, 2014). Aberrant reaction of the microcirculation characterized by movement of fluid and leukocytes from the blood into extravascular tissues. "The levels expression of 21 genes, including ADRA2B, CNR1 and LEP were significantly altered in the gastric tissue of NAFLD patients with hepatic inflammation." (PMID 24716593, 2014).
metabolic disorders (1 paper, 2023). "On the other hand, single nucleotide polymorphisms at the ADRA2B locus are associated with variations in the basal metabolic rate in obese populations and adult metabolic disorders." (PMID 38093359, 2023).
neurological diseases (1 paper, 2022). "Both agonists and antagonists targeting ADRA2B were tested for multiple neurological diseases, such as bipolar disease, brain injury, and Parkinson’s disease (PD), but not ALS." (PMID 35837482, 2022).
ADRA2B also shares sentences with these, for which no sentence is quoted: cancer (2 papers); depression (2); migraine (2); Obesity (2); tumor (2); acute myocardial infarction (1); Anxiety (1); asthma (1); attention deficit-hyperactivity disorder (1); breast carcinoma (1); cavernous hemangioma (1); colon cancer (1); dilated cardiomyopathy (1); epilepsy (1); hypotension (1); memory impairment (1); mental disorder (1); neuropathy (1).